GLI1 (GLI family zinc finger 1)
Diseases named in the same sentence as GLI1 in open-access papers (continued):
Sharing a sentence is not in itself a finding about the gene and the disease.
tumor (continued). "Taken together, circIPO11-mediated GLI1 upregulation enhances Hh signaling activation that initiates the self-renewal maintenance of liver CSCs and tumor propagation." (PMID 34649567, 2021). "Tamoxifen-mediated effects on tumor growth, expression of Gli1 and on myogenic differentiation markers were also excluded." (PMID 34172934, 2021). "In GSCs, specific disruption of the SHH/GLI1 axis dictates the chemoresistant and radioresistant properties of the tumor and ultimately disease prognosis." (PMID 34012965, 2021). "The activation of the Shh–Gli1 pathway was assessed through immunohistochemistry (IHC) of Gli1 and RT-qPCR analysis of the transcripts of Gli1 target genes in 14 available tumor biopsies collected at diagnosis (baseline)." (PMID 34970481, 2021). "Immunoblotting results of tumor tissues also showed that the protein levels of GLI1 decreased in XH30 and TMZ combination group compared to vehicle group." (PMID 34899305, 2021). "As a transcription factor, GLI1 can change tumor chemoresistance via epigenetic regulation of some chemotherapy targets." (PMID 34659557, 2021). "Shh pathway activation was assessed by the mean of the nuclear staining through IHC of Gli1, in tumor tissue samples from 14 patients with known Shh plasma concentrations." (PMID 34970481, 2021). "The present research also revealed that MVP, as a crucial GLI1 regulator enhances proliferation to tumor cells and anti-apoptosis process." (PMID 33637972, 2021). "We observed GLI1 was highly expressed in the tumor tissues of HCC patients in the TCGA database, and the expression levels were consistent with clinicopathological stages." (PMID 33500560, 2021). "A recent study has shown that pristimerin exerts inhibitory effects on tumor angiogenesis through suppressing Shh/Gli1 and its downstream pathways in non-small cell lung cancer (NSCLC)." (PMID 34026649, 2021). "Gli-1 appears to play a pivotal role in the maintenance of tumor cells with stemness characteristics." (PMID 33639931, 2021). "PTCH1 and GLI1 mRNA expression as an indication of the canonical SHH signaling pathway activity in tumor malignancy." (PMID 33391411, 2021). "Among the down-regulated genes, GLI1 and some other tumor progression related genes were discovered, for example, MMP1, MMP9, NFKB2, TGFA, and EGFR." (PMID 33637972, 2021). "Immunohistochemical staining of AA- and WA-TNBC tissues showed nuclear localization of NICD and GLI1 in tumor tissues with varying degrees of heterogeneity." (PMID 34889737, 2021). "Our observation of GLI1 as a tumor suppressor is in agreement with other reports on Hh signaling in NB." (PMID 33921042, 2021). "A phosphoglycoprotein named Osteopontin, expressed strongly in tumor stromal cells, activated GLI1 expression and transcriptional activity by domineering AKT-GSK3β." (PMID 34203598, 2021). "Although we detected overexpression of Gli1 in the three tumor cell lines, by means of the luciferase assay, we observed that this pathway was only active in the U87MG line." (PMID 34073238, 2021). "GLI1 also associates with increased angiogenesis in TNBC as GLI1 overexpression pairs with VEGFR2 and its inhibition reduces tumor angiogenesis." (PMID 34889737, 2021). "Thirty-six patients (66.7%) had a corresponding tumor sample with enough tumor cells available for Gli1 and beta-catenin immunohistochemistry (IHC)." (PMID 33807552, 2021). "GANT-61 (GLI1/2 inhibitor) can inhibit tumor cell proliferation and block tumor growth in ARMS and ERMS animal models by inhibiting the Shh/AKT–mTOR signaling axis." (PMID 34221974, 2021). "GLI1 overexpression significantly accelerates tumor growth and upregulated p-AKT, CDK4, and cyclinD3 in vivo." (PMID 33658491, 2021).
tumor (continued). "To check if the Shh pathway is active in our tumor cell lines, we performed an RT-qPCR against Gli1 and a luciferase assay." (PMID 34073238, 2021). "Positive Gli1 expression is associated with poor-prognosis gross and histological types, advanced TNM tumor classification, and large tumor size." (PMID 32478377, 2020). "In this regard, our study provides strong evidences for the vital role of Shh/Gli1 in tumor angiogenesis and indicates that targeting Shh/Gli1 is a potential strategy for suppressing tumor angiogenesis." (PMID 32286274, 2020). "In order to evaluate the expression of HH pathway components in canine OSA tumor tissues we performed in situ hybridization for canine Ihh, Smo, Ptch1, Gli1, and Gli2 mRNA on archived, formalin fixed, paraffin-embedded primary canine OSA samples." (PMID 32348319, 2020). "We used IHC to detect the GLI1 protein, a marker of Hh signaling in 127 cases of GC and matched non-tumor tissues." (PMID 33170154, 2020). "The cytotoxic activity of the GLI1 inhibitor was evaluated after 72 h of incubation in different human tumor cell lines, using an alamarBlue assay." (PMID 32846867, 2020). "Most tumor types exhibited similar correlation values between GLI1 expression and that of at least one of either HH or TGFB genes." (PMID 32879407, 2020). "Simultaneously, we demonstrated that IBET-151 treatment attenuates GLI1 transcription by reducing BRD4 occupancy on the GLI1 locus in both EAC47 cells derived from a patient tumor and OE33 cell line." (PMID 32913560, 2020). "The findings of this study illustrated that the Shh/Gli1 pathway was aberrantly activated in GC cell lines and tumor tissues, and that it contributed to the migration and invasion of GC cells." (PMID 32328197, 2020). "The use of a preclinical model of ES demonstrates that GANT61, an inhibitor of the transcriptional factor Gli1, reduces ES primary tumor growth." (PMID 33228057, 2020). "In order to assess Shh pathway activation in GC, we first used immunohistochemistry to examine the protein expression of Shh pathway members (Shh, Ptch, Smo and Gli1) in GC and adjacent non-tumor tissue samples." (PMID 32328197, 2020). "A significant difference in GLI1 expression was observed between GC and non-tumor tissues (P < 0.01)." (PMID 33170154, 2020). "The results indicated that expression of Shh, Ptch1, Smo and Gli1 protein was upregulated in GC tissues in comparison with adjacent non-tumor tissues." (PMID 32328197, 2020). "Since EAC cell lines with ectopic expression of GLI1 had increased expression levels of HH target genes and GLI1 depletion decreased the tumor ability to form colonies, we conclude that GLI1 is a critical regulator of EAC maintenance." (PMID 32913560, 2020). "In order to understand the role of Hh signaling in VM in GC, we detected the expression of GLI1 in 127 GC tissues and matched non-tumor tissues." (PMID 33170154, 2020). "The ISH evaluated cellular gene expression of Ihh, Smo, Ptch1, Gli1, and Gli2 mRNA both in neoplastic cells and stromal cells comprising the tumor microenvironment." (PMID 32348319, 2020). "Taken together, our study showed that pristimerin was a promising novel anti-angiogenic agent for the NSCLC therapy and targeting Shh/Gli1 signaling pathway was an effective approach to suppress tumor angiogenesis." (PMID 32286274, 2020). "To provide a biological meaning of the GLI1 and GLI2 genes in lung cancer, we used the Xena browser analysis for comparison of normal and tumor GLI gene transcripts." (PMID 32033067, 2020). "For example, analysis of primary esophageal cancers revealed that even though the SHH transcript was localized to the tumor tissue, expression of GLI1 and PTCH1 was found in both the tumor and stroma." (PMID 32957513, 2020). "GLI1 is associated with tumor formation in PDAC, and GLI1 knockout in PDAC cells inhibits cell proliferation and prevents tumor formation." (PMID 32859041, 2020).
tumor (continued). "Using a GBM xenograft mouse model, we showed that tGLI1-expressing tumor cells were significantly more infiltrative than GLI1-expressing cells thus promoting the aggressiveness of GBM." (PMID 32957513, 2020). "The reduction of tumor mass in the preclinical model is explained by the decrease in the expression of GLI1 and PTCH1." (PMID 33179013, 2020). "In most of them, only GLI1 of the three GLI proteins was stained, and its nuclear localization was associated with metastasis, poor survival, tumor size, and recurrence." (PMID 32899202, 2020). "For the GC tissues, the median GLI1 IHC score was 65.08 (6.73-164.78), whereas that of the matched non-tumor tissues was 35.21 (3.16-98.12)." (PMID 33170154, 2020). "Results showed that Gli1 expression was closely related to tumor grade, primary tumor (pT) stage, distant metastasis, clinical stage, gross type, microvessel density, and shorter overall survival (OS)." (PMID 32430068, 2020). "This indicated a rate of positive GLI1 expression in GC tissues of 39.4% (50/127), and 8.66% (11/127) in the matched non-tumor tissues, which is a significant difference (χ2 = 32.81; P < 0.01)." (PMID 33170154, 2020). "Although numerous studies have confirmed that the Hh/GLI1 pathway promotes tumor invasion and metastasis, the role of Hh/GLI signaling in VM has not been previously studied." (PMID 33170154, 2020). "The results revealed that 74.2 % (132/178) of the GC tissues were positively stained for Gli1, which was a much higher percentage than that detected in the adjacent non-tumor tissues (36.0%; 32/89; P<0.001)." (PMID 32328197, 2020). "The upregulation of downstream effectors in the HH signaling cascade such as GLI1 has been suggested as a possible mechanism to explain tumor resistance to the SMO inhibitors, as is the case with vismodegib." (PMID 32913560, 2020). "Regarding the transcriptional factors Gli1-3, most studies have focused on the role of the transcription factor Gli2 in OS tumor development and progression." (PMID 33228057, 2020). "In this study, we showed that pristimerin suppressed tumor angiogenesis in NCI-H1299 xenografts via inhibiting Gli1 nucleus distribution in endothelial cells and pericytes, and then inactivating Shh/Gli1 and its downstream signaling pathway." (PMID 32286274, 2020). "Immunohistochemical analysis for NICD1, β-catenin, and GLI1 was performed to confirm the in vivo results in the ZBC260-exposed tumor cells of mice." (PMID 33093476, 2020). "In most tumor types, GLI1 and GLI2 follow a similar pattern of expression and are equally correlated with HH and TGFB genes." (PMID 32879407, 2020). "The transcription factor Gli1 appears particularly important in ES, as it is overexpressed in patient tumor specimens and in ES cell lines." (PMID 32110934, 2020). "Altogether, our study demonstrated that pristimerin suppressed tumor growth and angiogenesis by inhibiting Shh/Gli1 signaling pathway in NCI-H1299 xenografts." (PMID 32286274, 2020). "Further research revealed that pristimerin suppressed tumor angiogenesis by inhibiting the nucleus distribution of Gli1, leading to inactivation of Shh/Gli1 and its downstream signaling pathway." (PMID 32286274, 2020). "In the present work, we confirmed the close similarities between TB tumor cells and epithelial MC progenitors, evident by expression of GLI1 and its related downstream targets, i.e., KRT17 and SOX9, in both settings." (PMID 32708246, 2020). "In the present study, we demonstrated that Shh stimulation promoted pericytes adhesion and recruitment to endothelial tubes and pristimerin suppressed tumor angiogenesis by inhibiting Shh/Gli1 signaling pathway." (PMID 32286274, 2020). "For instance, in prostate cancer specimens, the expression of HH was detected in the tumor epithelium, while GLI1 expression was found in the tumor stroma cells, suggesting their paracrine crosstalk." (PMID 32531973, 2020).
tumor (continued). "Dysregulation of the Hh pathway observed in MB and other tumours can be caused by ligand-independent events, such as genetic mutations of pathway components (PTCH, SMO, SuFu, REN, GLI1/GLI2 amplification) or ligand-dependent mechanisms of activation." (PMID 30699938, 2019). "The analyses revealed that, despite lack of Sonic HH (SHH) expression, a subset of human cSCC can express GLI1, a marker for active HH signaling, within distinct tumor areas." (PMID 31867038, 2019). "Upregulation of GLI1 is common in BC compared to normal mammary tissue and correlates with tumor grade, invasiveness and metastasis." (PMID 31027259, 2019). "Hh ligands (including DHH) produced by tumor cells lead to Gli-1 mediated “M2-polarization” of macrophages which is associated with immunosuppression and pro-tumorigenic activity." (PMID 31788004, 2019). "In contrast to positive expression of PTCH1 and GLI1 in our findings, it is essential to show that tumor cell RNA is preserved and available for hybridization." (PMID 30769952, 2019). "In BxPC3-GR cell line in which GLI1 is up-regulated, knockdown of GLI1 reduced the size of tumor spheres." (PMID 30382189, 2019). "Compound 22 was able to inhibit Hh-dependent tumor growth in human and murine MB cells at sub-micromolar concentration, as a consequence of the reduction in Gli1 expression levels." (PMID 31601026, 2019). "Nilotinib also reduced tumor volume in a mouse MB xenograft model, and suppressed Gli-1 mRNA in both in vivo and ex vivo tumor cells." (PMID 31539380, 2019). "Tumor growth was suppressed by treatment with Hh inhibitors, and this inhibitory effect correlated with the downregulation of GLI1 and PTCH1 levels in fibroblasts." (PMID 31658643, 2019). "Based on the inverse correlation between the expression of Sufu and Gli1, specifically after vismodegib treatment, we propose that vismodegib sensitizes tumor cells to SUFU-mediated inhibition by reducing stimulation through SMO and SMOM2." (PMID 31863004, 2019). "Oral administration of the drug in mouse MB genetic engineered models led to complete inhibition of GLI1 and tumour regression." (PMID 31362788, 2019). "GLI1 signaling impacts multiple cancer-relevant cellular processes, promoting dedifferentiation, the generation of CSCs, tumor progression, and metastasis." (PMID 31057614, 2019). "Bioluminescence imaging demonstrated a marked reduction of tumor cell proliferation, while levels of GLI1 and PTCH2 transcripts were reduced in cells from tumor samples." (PMID 31480477, 2019). "Abnormal activation of GLIA and GLI1 represents a critical parameter for both tumor initiation and progression." (PMID 31244888, 2019). "We observed that GLI1 mRNA expression is higher in the primary tumor samples than in normal solid tissues (p < 0.05)." (PMID 31783569, 2019). "GLI1 gene targets sustain proliferation, inhibit apoptosis, promote angiogenesis and promote tumor cell migration." (PMID 31085420, 2019). "Compared to controls, mice engrafted with GCPs overexpressing ERAP1 showed an increased tumor growth rate, tumor volume (at the end point), and expression of Gli1 and CyclinD2, accordingly with the role of ERAP1 in promoting Hh signaling." (PMID 31341163, 2019). "GLI1 inhibition and overexpression confirmed that IL-24-mediated anti-tumor effects involved the GLI-dependent pathway." (PMID 31783569, 2019). "Patients with more sonidegib exposure had more reduction in GLI1 mRNA expression in the tumor compared with matching normal skin samples." (PMID 31035664, 2019). "The results of further IHC studies of these three molecules indicated that the PKA and SUFU protein were mainly localized in the cytoplasm of tumor cells, while the GLI1 protein was mainly localized in the cytoplasm and nucleus." (PMID 31519191, 2019).
tumor (continued). "Aberrant expression of GLI1 is responsible for aggressive tumor behavior and survival due to its effects on the DNA damage response (DDR)." (PMID 31783569, 2019). "Control of GLI1 expression is critical for cell proliferation and its abnormal regulation leads to tumor progression." (PMID 29662197, 2018). "Nox4 promoted cell proliferation via activation of the GLI1 pathway and overexpression of GLI1 reversed the suppression of tumor cell growth induced by silencing NOX4." (PMID 30513726, 2018). "PTCH1, SHH, DHH, and GLI1 over-expression were observed in 74%, 95%, 92% and 98% tumour specimens of the cohort." (PMID 29329585, 2018). "IHC staining was undertaken to evaluate the expression of Hh pathway components (SHH, PTCH1 and GLI1) in the primary tumour and their respective adjacent histologically normal epithelium." (PMID 30379908, 2018). "Treatment with 1 produced a significant reduction in tumor growth compared with vehicle, consistently with decreased expression of GLI1 mRNA." (PMID 29396391, 2018). "Several studies documented the lack of efficacy of SMO inhibitors, alone or in combination with chemotherapy, in a range of tumours, even though in some cases, a reduction in GLI1 expression levels was observed in tumour tissues." (PMID 30068568, 2018). "In the present study, we showed that Hedgehog inhibitor increased the sensitivity for anti-cancer drugs and decreased expression of CD44, c-Myc and Nanog likely through the inhibition of GLI-1 in tumor ALI organoids." (PMID 29642386, 2018). "While the Shh pathway is closely associated with CSCs, which represent less than 1% of tumor cells, the majority of NSCLC cells show positive Gli1 and Gli2 expression by immunohistochemistry, suggesting a complex mechanism of Shh pathway activation in NSCLC." (PMID 29581874, 2018). "GLI1 is well understood to positively regulate cell proliferation through direct transcriptional upregulation of cyclinD/E, Rb tumor suppressor inhibitors, c-Myc, and other pro-proliferative genes." (PMID 29930746, 2018). "The level of nuclear Gli1 is closely related to the pathological grade of tumours; invasive and metastatic abilities of the tumour; and levels of phosphorylated ERK1, phosphorylated ERK2 and MMP-9." (PMID 29899399, 2018). "As a consequence, glabrescione B prevents binding of GLI1 to DNA, impairs its transcriptional activity, and reduces the growth of Hh-dependent tumor cells in vitro and in vivo, as well as the self-renewal ability and clonogenicity of tumor-derived stem cells." (PMID 29695137, 2018). "Paired non-parametric comparisons of average tumour expression showed an increase in the expression of SHH ligand (p<0.001), PTCH1 (p<0.001) and cytosolic GLI1 (p = 0.002) in the primary tumour compared to the adjacent histological normal epithelium." (PMID 30379908, 2018). "Consistently, our investigation showed that downregulation of Gli-1 substantially suppressed the mitosis of LN229 cells and consequentially increased cell apoptosis, suggesting a potential role of Gli-1 downregulation in the control of GBM tumor growth." (PMID 29867331, 2018). "In untreated PDX tumours, SHH and IHH were transcribed predominantly in the human-derived tumour epithelium, while Gli1, Ptch1 and Smo were transcribed predominantly in the murine stroma." (PMID 29715275, 2018). "Mean mRNA values of SHH, DHH and GLI1 showed gradual increase with tumour size, nodal spread and distant metastasis." (PMID 29329585, 2018). "As expected, mice injected with Gli1-shRNA cells got a slower tumor growth and a steady weight relatively." (PMID 29321573, 2018). "Gli1 expression varied by histotype of the tumor with high Gli1 expression being most common in serous tumors." (PMID 30042330, 2018). "Immunohistochemistry and western blot analysis of SCLC human samples and cell lines showed an overexpression of Shh and Gli1 in tumor and cancer cells." (PMID 29581874, 2018).